MIR6797 (microRNA 6797)
Synonyms: hsa-mir-6797
Gene: MicroRNA gene on chromosome 19 (41,869,627 to 41,869,698, forward strand). Ensembl gene ENSG00000276926.
Homologues: Orthologues: chimpanzee MIR6797 (100% identical).